CD4 (CD4 molecule)
Diseases named in the same sentence as CD4 in open-access papers (continued):
Sharing a sentence is not in itself a finding about the gene and the disease.
HIV-1 infection (continued). "An obvious advantage of KI over LV was a higher degree of CD4 lymphocyte protection from HIV-1 infection measured in cocultures with Raji effector cells." (PMID 35073736, 2022). "In CD4 + T-cells from spleens of humanized mice, they have noted that HIV-1 infection upregulates the expression of TRAIL receptor death receptor 5 (DR5) but not death receptor 4 (DR4)." (PMID 35185920, 2022). "During 2010–2016, the HIV-1 epidemic showed three new changes: the median age continued to decline, the cases with a CD4 count more than 500 cells/μl (CD4hi cases) disproportionally expanded, and the recent HIV-1 infection rate steadily increased." (PMID 36504809, 2022). "Indices of severity of HIV-1 infection, viral load and blood CD4+ cell counts were compared between HbAA and HbAS individuals with HIV-1 infection." (PMID 36685019, 2022). "Human epithelial cells, and more specifically, basal keratinocytes, are exclusive targets for HPV, while CD4+ immune cells, such as T helper cells, monocyte/macrophages, dendritic cells, etc., are the major targets for HIV-1 infection." (PMID 35453518, 2022). "Using the human primary intestinal lamina propria monocyte model, the exposure of human primary intestinal lamina propria monocytes to E. coli will enhance HIV-1 infection of CD4 T cells and promote T cell apoptosis in vitro." (PMID 35129067, 2022). "Similar to T cell activation, earlier studies have characterized how HIV-1 infection in CD4+ T cells upregulates glycolysis to meet the energy-demanding turnover for virion production, simultaneously depleting CD4+ T cells." (PMID 35005552, 2022). "Altered glutaminolysis (i.e., glutamine lysed to glutamate) and increased plasma glutamate have been observed in several cohorts from both high income and low- and middle-income countries and are required for optimal HIV-1 infection of CD4+ T cells." (PMID 35537851, 2022). "HIV-1-induced expression of TSLP in epithelial cells triggers dendritic cell (DCs)-mediated amplification of HIV-1 infection in activated CD4+ T cells." (PMID 36313221, 2022). "Conversely, another study showed that YTHDF readers recognize m6A-modified HIV-1 RNA and inhibit HIV-1 infection in CD4 + cells by decreasing HIV-1 reverse transcription." (PMID 36085064, 2022). "Song found that the expression of Caspase-1 increased rapidly and then decreased within a short period of time in the high CD4+ T cell counts group during the early stage of HIV-1 infection." (PMID 36411423, 2022). "We found that CD98high CD4+ T cells are hyper-permissive for HIV-1 infection and display distinct immune phenotypes." (PMID 36214569, 2022). "We also applied single-cell transcriptome sequencing to a primary cell model of early HIV-1 infection using CD4+ T cells from healthy donors." (PMID 36175869, 2022). "The presence of high levels of antiviral restriction factors have shown to restrict HIV-1 infection in resting CD4 T cells." (PMID 35359982, 2022). "Direct co-culture of infected and uninfected cells resulted in significant levels of HIV-1 infection of resting CD4+ target T cells (Gag+) measured by intracellular flow cytometry staining." (PMID 35417711, 2022). "According to previous reports, central memory CD4+ T cells are the major cellular reservoir for HIV-1 infection." (PMID 36214569, 2022). "After HIV-1 infection of primary CD4+ T cells, the oxygen consumption rate (OCR), a measure of OXPHOS, was found to be decreased showing the reliance on glycolysis rather than OXPHOS." (PMID 36467738, 2022). "We analyzed the usage of V(D)J genes among individuals with chronic HIV-1 infection and HDs and investigated the gene preference of TCRs in CD4+ T cells across the three conditions." (PMID 35351857, 2022). "Since these cells are not restored in the GALT during ART, it can be postulated that the CD4+CCR6+ cell population is a major target for HIV-1 infection that in PLWH contributes to the inflammatory environment in both GALT and peripheral blood." (PMID 35418589, 2022).
HIV-1 infection (continued). "We have previously shown that functional antagonism of S1P receptors reduces cell-free, cell-to-cell, and latent HIV-1 infection in primary CD4 T cells." (PMID 35412343, 2022). "The mechanism of systemic CD4 T cell depletion during acute HIV-1 infection in vivo remains to be determined." (PMID 36000842, 2022). "The model supported HIV-1 infection with depletion of CD4+ T cell counts and high plasma viremia and responded to antiretroviral therapy (ART) with no detectable viremia or CD4+ T cell depletion." (PMID 34818071, 2022). "In HIV-1 infection, along with CD4+ T lymphocytes, MΦ serve as vectors for virus dissemination and as viral reservoirs, impeding HIV-1 eradication." (PMID 35622876, 2022). "Many of these studies have focused on the effect of HIV-1 on CD4+ T cells and have identified key pathways that are important for the regulation of HIV-1 infection and latency." (PMID 36175869, 2022). "Taken together, and in light of our previous report that S1PR inhibition reduces HIV-1 infection, our results indicate that the conversion of sphingosine to S1P by SPHK facilitates HIV-1 infection of CD4 T cells." (PMID 35412343, 2022). "To identify genes that are critical for regulating CD4+ T cell resistance or sensitivity to initial HIV-1 infection, we used scRNA-seq in a primary CD4+ T cell model of HIV-1 infection." (PMID 36175869, 2022). "Due to the cytotoxicity roles and clonal expansion of CD8+ T cells, the loss of the naive CD8+ subset was more obvious compared with that of the naive CD4+ subset upon HIV-1 infection." (PMID 35351857, 2022). "Selected sgRNA effectively disrupted the CCR5 gene, and the CCR5-disrupted CD4+ T cells showed increased resistance against HIV-1 infection." (PMID 35628210, 2022). "Autophagy, a pathway of cellular degradation independent of caspase-induced cell death, was also reported to occur within bystander CD4 T cells during ex vivo HIV-1 infection, contributing to CD4 T cell depletion." (PMID 36000842, 2022). "Viral DNA load and the plasma viral RNA load at comparable CD4+ T-cell counts are significantly lower in HIV-2 compared with HIV-1 infections." (PMID 36366545, 2022). "In order to determine the role of ISG15 in HIV-1 infection in primary CD4+ T cells, we infected the ISG15KO CD4+ T cells with HIV-1." (PMID 35333911, 2022). "S1P binds to S1PR on CD4 T cells to initiate various signaling cascades, and we have previously demonstrated that inhibition of S1PR on primary CD4 T cells inhibits HIV-1 infection." (PMID 35412343, 2022). "Authors suggest that low expression of JNK in primary resting CD4+ T cells from peripheral blood restricts efficient HIV-1 infection." (PMID 36293197, 2022). "Selected sgRNA efficiently induced editing of the CXCR4 gene in human CD4+ cell lines and made these cell lines resistant to HIV-1 infection." (PMID 35628210, 2022). "Our lab previously developed a primary T cell model of acute HIV-1 infection in quiescent CD4 T lymphocytes." (PMID 35895672, 2022). "Altogether, the metabolism of cells targeted by HIV-1, either CD4+T cells or macrophages, emerges as an important common determinant of HIV-1 infection, even if regulated by different mechanisms." (PMID 36220814, 2022). "We have previously shown that short-term IL-15 treatment of HIV-specific CD8+ T cells from noncontrollers increased the capacity of these cells to mobilize mitochondrial activities and suppress HIV-1 infection of CD4+ T cells." (PMID 35380989, 2022). "On the contrary, the expression of Caspase-1 increased significantly in the low-level CD4+ T cell counts group after one year of HIV-1 infection." (PMID 36411423, 2022). "Along the course of untreated HIV-1 infection, as the viral load progressively increases, the immune function collapses due to the depletion of circulating CD4+ T-cells." (PMID 35181598, 2022). "Knockdown of HDAC10 in CD4+ T cells with specific shRNAs was shown to benefit HIV-1 infection, specifically facilitating an integration step." (PMID 36293197, 2022).
HIV-1 infection (continued). "In line with this possibility, recent studies suggest that mDCs treated with adjuvants targeting TBK1 are associated with reduced depletion of CD4+ T cells and polyfunctional HIV-1 specific CD8+ T cells in humanized mice after HIV-1 infection." (PMID 36569826, 2022). "Inhibiting PPARγ also prevented robust CD4+ T cell activation which is necessary for HIV-1 infection." (PMID 36467738, 2022). "In humanized mice, CD4+ T cells expressing C34-CXCR4 were highly resistant to HIV-1 infection and had a selective survival advantage, and it has now been advanced to clinical trials." (PMID 34821542, 2022). "IMPORTANCE Different mechanisms for CD4 T cell depletion during acute HIV-1 infection have been proposed." (PMID 36000842, 2022). "Intriguingly, upon HIV-1 infection, the intimate cell-to-cell contacts formed between DCs and CD4+ T cells can boost viral transmission via the formation of an ‘infectious synapse’ that allows for systemic HIV-1 dissemination." (PMID 35055987, 2021). "The deubiquitination enzyme USP8 is a human T cell-specific factor regulating T-cell maturation and functions, and CD4+ T cells are primary targets of HIV-1 infection." (PMID 34630422, 2021). "In sum, HIV-1 infection and entry into CD4+ T cells triggers rapid, dynamic, and genome-wide changes in the host transcriptome; as a general trend, the magnitude of expression changes tended to be greater for upregulated genes than for downregulated genes." (PMID 34154423, 2021). "Addition of 4-1BB to CD4 based CARs led to faster suppression of viremia during early untreated HIV-1 infection." (PMID 33793675, 2021). "Re-expressing LAPTM5 reconstituted the Vpr-dependent promotion of HIV-1 infection in primary CD4+ T cells, as observed in macrophages." (PMID 34140527, 2021). "In our study, miR-29-x was predicted to target the DETmR AP-1 complex subunit gamma-1 (AP1G1), which in mammals is known to affect HIV-1 infection by influencing the process of HIV-mediated CD4 internalization and targeting to lysosomes." (PMID 33808870, 2021). "Flow cytometry analysis and immunofluorescence microscopy showed increased platelet-CD4+ T cell aggregate formation in TNs compared to HCs during HIV-1 infection." (PMID 34987521, 2021). "Almost all of our clustered study participants presented with late HIV-1 infection (CD4 count < 350 cells/μL), suggesting that HIV acquisition likely occurred prior to arrival in Canada." (PMID 33915869, 2021). "The significant decrease in the observed lamina propria CD4+ LPLs immune activation is an important finding, especially in the context of mucosal dysfunction that is observed in HIV-1 infection immunopathogenesis." (PMID 34442703, 2021). "The GLUT1-mediated metabolic pathway is essential for HIV-1 infection in human CD4+ T cells and thymocytes 44,51,52." (PMID 33391506, 2021). "We found that CD2 ligation with its cell-free ligand LFA-3 or anti-CD2 antibodies rendered blood resting CD4 T cells highly resistant to HIV-1 infection." (PMID 34765923, 2021). "In the second method we tested the ability of the compounds to act as pre-exposure prophylaxis treatment, treating CD4 T cells with the AZT derivatives for 18 h prior to HIV-1 infection (method two)." (PMID 34771129, 2021). "Most of the attention on the impact of CTL activity has been on HIV-1 infection of CD4+ T cells while the impact of CTL on HIV-1 infection of macrophages has been understudied." (PMID 33897659, 2021). "As macrophages express the HIV-1 entry receptor CD4 and co-receptors CCR5 and CXCR4, they are themselves susceptible to HIV-1 infection." (PMID 33669846, 2021). "In the early stages of HIV-1 infection, the virus is able to undermine the T cell immune response by infecting CD4+ T cells, thus reducing their numbers and impairing their function, which ultimately contributes to viral immune escape." (PMID 34198973, 2021).
HIV-1 infection (continued). "Comparing total virus output from infected PBMCs and CD4+ T-cells at days of peak replication, revealed that although CD4+ T-cells from LVLs supported HIV-1 infection, significantly less virus was produced compared to normal donors." (PMID 34122382, 2021). "As in DCs, HIV-1 infection inhibits autophagy in human CD4+ T cells, via HIV-1 Vif interactions with LC3, and a HIV-1 Nef-dependent block in autophagy flux resulting in accumulation of endosomes and lysosomes." (PMID 33669846, 2021). "The patient’s PMH included HIV-1 infection (undetectable viral load and CD4+ cell count 743), DM with retinopathy and stage 3b CKD and HT." (PMID 34201947, 2021). "Using selected single-guided RNA and lentivirus expressing SaCas9, CXCR4-modified primary CD4+ T cells were generated that proliferated normally and successfully established resistance to HIV-1 infection." (PMID 34122453, 2021). "As the baseline diversity increases, it appears that the CD4+/CD8+ ratio decreases dramatically post-HIV-1 infection for SC." (PMID 34879869, 2021). "CD4+ T cell interactions with activated platelets exhibited phenotypic characteristics with permissive to HIV-1 infection and was related to immune activation during HIV-1 infection." (PMID 34987521, 2021). "By diminishing the amount of immune activation, CD4+ T cell depletion and VLs in untreated infection, what results is fewer target cells for HIV-1 infection, preservation of the immune response, and a lower burden of viraemia over time." (PMID 34344423, 2021). "This modification of CD4+ T cells allowed inhibition of HIV-1 infection and resulted in a significant reduction in viral load, as measured by p24 ELISA and qRT-PCR." (PMID 35126374, 2021). "Increasing CD4+ T cell loss and an increase in CD8+ T cells are consistent features of HIV-1 infection." (PMID 33937149, 2021). "Activated effector CD4+ T cells represent a primary target for HIV-1 infection due to their high permissiveness and metabolic state relative to resting cellular subsets." (PMID 34344423, 2021). "We analyzed HIV-1 integration sites from resting and activated CD4+ T cells during primary HIV-1 infection, collected as early as 22 days after estimated day of infection." (PMID 33784259, 2021). "HIV-1 infection of CD4+ T cells stimulates cholesterol biosynthesis via SREBP2 sterol response gene (protein TFII-I) activation for enhanced HIV-1 transcription and HIV-1 replication." (PMID 33757439, 2021). "It is well known that PD-1 expression correlates with the impairment of CD8 T-cell functionality, increased viral load, and reduced CD4 T-cell counts in HIV-1 infection (40, –, 46)." (PMID 34523962, 2021). "We compared the fate of HIV-1 infections in macrophages, unstimulated CD4+ T cells, and CD4+ T cells activated through the CD3/CD28 signaling axis." (PMID 34962974, 2021). "Chronic immune activation (CIA) and CD4+ T-cell depletion are two important markers of HIV-1 infection." (PMID 33567490, 2021). "In HIV-1 infection, the establishment of viral latency in CD4+ T cells presents a major barrier to the elimination of HIV-1-infected cells as these latently infected cells do not express HIV viral proteins and thus are not immunogenic." (PMID 33647028, 2021). "These previous studies provide a rationale for targeting CD2 to block HIV-1 infection of blood CD4 T cells." (PMID 34765923, 2021). "HIV-1 infection is associated with increased CCR5 density on T cells, particularly CD4+ T cells; however, we observed the opposite in that HIV-1-infected controllers expressed CCR5 at lower densities compared to HCs within these same cell subsets." (PMID 34987508, 2021). "In this study, CCR5 and CXCR4 were both overexpressed on platelet-CD4+ T cell aggregates compared to their counterparts and were upregulated during HIV-1 infection, indicating that these cells were more permissive to R5 and X4 HIV-1 strains." (PMID 34987521, 2021).
HIV-1 infection (continued). "ZFNs have been utilized to confer resistance to HIV-1 infection in resting CD4+ T cells through the disruption of the CCR5 gene in humanized mouse models." (PMID 33868262, 2021). "In the early stage of HIV-1 infection, several pathological and immunological events such as CD4+ T-cell depletion, the establishment of a virus reservoir, a cytokine storm, and immune activation are induced, and each is associated with disease progression." (PMID 33924786, 2021). "In contrast, humanized mice contain human CD4+ T cells, which are permissible to HIV-1 infection and simultaneously allow in-depth analysis of the human immune response to HIV-1 pathogenesis in vivo." (PMID 33868262, 2021). "In untreated HIV-1 infection progressively increased expression of PD-1 on both CD4 and CD8 T-cell subsets have been demonstrated in patients with long-follow-up." (PMID 34712231, 2021). "The establishment of the inflammatory state occurs early in HIV-1 infection, as shown by the increase in activation markers like HLA-DR highlighting their contribution to CD4+ T-cell activation." (PMID 34578386, 2021). "Our data on RIGs show that similar patterns of HIV-1 integration occur in different stages of HIV-1 infection in resting as well as in activated CD4+ T cells." (PMID 33784259, 2021). "Memory CD4 T cells are major targets of HIV-1 infection, and early depletion of memory CD4 T cells in the gastrointestinal tract by the CCR5 (R5)-utilizing T-tropic virus is a major cause of chronic immune activation in patients." (PMID 34765923, 2021). "These transgenic HSCs bearing the mutated TRIM5α would be implanted to achieve long-term cell repopulation in order to generate a durable subset of CD4+ T cells resistant to HIV-1 infection as reported with the CCR5 gene." (PMID 33995324, 2021). "RBC viral traps neutralized HIV-1 in vitro at 2,500-fold lower concentrations than the concentration of total RBCs in human blood and reduced HIV-1 infection of CD4+ T cells by 70% at an RBC-to-T cell ratio of 5:1." (PMID 33723514, 2021). "Landmark studies carried out in the 90s in the laboratory of Ralph Steinman showed that the efficacy of HIV-1 infection of CD4+ T cells was increased when DCs were added in co-culture as compared to the transmission of cell-free viruses." (PMID 35055987, 2021). "A curative therapy for HIV-1 infection will at least require the eradication of a small pool of CD4+ helper T cells in which the virus can persist in an inactive, latent state, even after years of successful antiretroviral therapy." (PMID 33465149, 2021). "As well, HIV-1 accessory protein, Nef is also excreted within exosomes and has a significant role in HIV-1 infection via assisting in CD4+ T cell depletion that is the target infection of HIV-1." (PMID 34575480, 2021). "It comprises the combined use of several drugs and can decrease the viral load and increase the CD4+ T cell count in patients with HIV-1 infection, thereby proving to be an effective modality." (PMID 34194504, 2021). "Next, HIV-1 infection in platelet-CD4+ T cell aggregates was analyzed based on intracellular HIV-1 p24 expression." (PMID 34987521, 2021). "In summary, characteristic HIV-1 integration site features are preestablished as early as during primary HIV-1 infection and are found in both resting and activated CD4+ T cells." (PMID 33784259, 2021). "Viral replication in HIV-1 patients is largely the consequence of a dynamic process involving continuous rounds of de novo HIV-1 infection of and replication in activated CD4+ T cells with a rapid turnover of free virus and virus-infected cells." (PMID 34834213, 2021). "HIV-1 infection and integration into tree shrew lung fibroblasts expressing exogenous human CD4 and CCR5." (PMID 34076481, 2021). "Platelets serve as an acute HIV-1 reservoir and a carrier to fuel the HIV-1 infection of CD4+ T cells through the formation of platelet-CD4+ T cell aggregates under co-culture conditions." (PMID 34987521, 2021).